TAB1 (TGF-beta activated kinase 1 (MAP3K7) binding protein 1)
Diseases named in the same sentence as TAB1 in open-access papers (continued):
Sharing a sentence is not in itself a finding about the gene and the disease.
gastric cancer (1 paper, 2022). A primary or metastatic malignant neoplasm involving the stomach. "The experimental results show that CXCR4 expression was higher in gastric cancer cells, while TAB1 expression was higher in normal gastric tissues than in gastric cancer tissues." (PMID 35509844, 2022). "The results demonstrated that the pathway could regulate the progression and immune microenvironment of gastric cancer by modulating the immune-gene signature, which included two immune genes (TAB1 and CXCR4)." (PMID 35509844, 2022).
glioma (1 paper, 2023). A benign or malignant brain and spinal cord tumor that arises from glial cells (astrocytes, oligodendrocytes, ependymal cells). "Moreover, FXYD6 was pertinent to the several classic EMT genes in gliomas (BMP2, TAB1, and so on) (|r| > 0.35, p < 0.05)." (PMID 38093622, 2023).
juvenile idiopathic arthritis (1 paper, 2023). Juvenile idiopathic arthritis (JIA) is the term used to describe a group of inflammatory articular disorders of unknown cause that begin before the age of 16 and last over 6 weeks. "A gene-set analysis indicated that IgG glycosylation (TAB1, MGAT3, and CACNA1I) and Response to methotrexate in juvenile idiopathic arthritis (CACNA1I and APOBEC3C) may engage common underlying genetic vulnerabilities." (PMID 37029179, 2023).
lung adenocarcinoma (1 paper, 2022). A carcinoma that arises from the lung and is characterized by the presence of malignant glandular epithelial cells. "Clinical analysis indicates that both GFAT1 and TAB1 S438 phosphorylation levels correlate with the poor prognosis of lung adenocarcinoma patients." (PMID 35945223, 2022). "Here, we found that GFAT1 facilitates TAB1-coupled p38 MAPK activation and contributes to lung adenocarcinoma cell survival under glucose deficiency through its positive effect on autophagy occurrence, pointing out GFAT1 could be a potential therapeutic target against lung adenocarcinoma." (PMID 35945223, 2022). "Our mechanistic study shows that GFAT1 along with TAB1 S438 phosphorylation contributes to p38 MAPK activation, thus we performed IHC analyses in serial sections of 87 human lung adenocarcinoma specimens to examine the clinical relevance of GFAT1, p-p38 level and TAB1 S438 phosphorylation levels." (PMID 35945223, 2022).
mastitis (1 paper, 2019). Inflammation of breast tissue during lactation or postpartum due to an obstructed duct or infection. "We found that SIRT7 can attenuate LPS-induced upregulation of TLR4 and TAB1 and can also inhibit TAK1 phosphorylation, indicating that SIRT7 is involved in the TLR4-TAK1-TAB1-mediated NF-κB signaling pathway during cattle mastitis occurrence." (PMID 31285783, 2019).
papillary thyroid cancer (1 paper, 2023). "TAB1 also regulates papillary thyroid cancer cell proliferation and migration." (PMID 36609391, 2023).
primary amyloidosis (1 paper, 2020). "The amyloidogenic light chain (AL-LC) protein activates p38α by TAB1-mediated p38α autophosphorylation in primary amyloidosis patients, causing oxidative stress, cellular dysfunction and apoptosis." (PMID 33204339, 2020).
seminoma (1 paper, 2021). A radiosensitive malignant germ cell tumor found in the testis (especially undescended), and extragonadal sites (anterior mediastinum and pineal gland).
Sepsis (1 paper, 2021). Sepsis is defined as life-threatening organ dysfunction caused by a dysregulated host response to infection. "It was a signal transducer upstream of p38 MAPK and NF-κB, while the inhibition of the interaction between TAK1 and TAB1 could attenuate TAK1-mediated MAPK activation, thereby alleviating sepsis-induced multiple organ dysfunction in mice." (PMID 34938184, 2021).
tumor (13 papers, 2013 to 2023). "Hsa_circ_0021727 attenuated the effect of miR-23b-5p in vivo.We detected the expression of hsa_circ_0021727, miR-23b-5p and TAB1 in mouse tumor tissues." (PMID 36609391, 2023). "We found that disruption of either JNK/p38-mediated phosphorylation or TAB1 glutamylation led to a suppressed tumor growth." (PMID 35945223, 2022). "The following immunoblotting analysis indicated that phosphorylation levels of TAB1, p-p38 level and autophagy flux in tumor tissues from WT group were notably enhanced in comparison with their basal levels shown in A549 cells cultured in vitro." (PMID 35945223, 2022). "MDM2 and TAB1 expression levels were associated with histological grading, whereas MDM2 and MDMX expression levels were associated with tumor size." (PMID 31892970, 2020). "That PTX combined with TAK1/TAB1 can be used in tumour disease treatment in the future needs to be verified in subsequent studies." (PMID 32594651, 2020). "We demonstrated that MDM2 and TAB1 expression was associated with histological grading, and that MDM2/MDMX expression was associated with tumor size." (PMID 31892970, 2020). "Analysis of TAB1 expression in tumor tissues confirmed that TAB1 protein was reduced by 70% in the knockdown clone when compared to that of control vector-transduced clone." (PMID 25557171, 2015). "We also examined the expression of the TAK1 binding partner TAB1 and found the up-regulation of TAB1 in 74% of the tumor tissues." (PMID 25557171, 2015). "The MEKK1 PHD is also required for TAB1-dependent ES-cell differentiation and tumour development in mice." (PMID 25260751, 2014). "We next investigated whether inhibition of the TAB1/TAK1 signaling (which reduced CCR7 expression) affects tumor metastasis." (PMID 25557171, 2015). "MAP3K7 requires TAK1-binding protein 1 (TAB1), TAB2, and TAB3 to trigger NF-κB activation, which is a key transcription factor for tumor initiation and malignancy." (PMID 31214512, 2019). "Previous studies demonstrated that miR-889 could regulate the tumor cellular behaviors by targeting serval target genes, such as KLF9, SIX1, DAB2IP, TAB1, FGFR2, TWEAK." (PMID 34116691, 2021). "Knockdown of TAB1 attenuated CCR7 expression and tumor growth in an orthotopic animal study." (PMID 25557171, 2015). "Add-back of TAB1, but not mTAB1, into Tab1−/− ES cells restored tumor development to WT levels." (PMID 25260751, 2014).
cancer (9 papers, 2020 to 2026). A tumor composed of atypical neoplastic, often pleomorphic cells that invade other tissues. "Glutamylation of TAB1 promotes its recruitment to p38α MAPK, which facilitates p38α MAPK autophosphorylation that is critical for the downstream events that support cancer cells survival under glucose deficiency." (PMID 35945223, 2022). "Since survivin, XIAP, TAB1 and TAK1 are involved in the anticancer effects of Sur-X, it can be inferred that Sur-X may have broader efficacy in cancer patients with high expression of survivin, XIAP, TAB1 and/or TAK1." (PMID 32381104, 2020). "To investigate whether TAK1 can cooperate with PTX for cancer treatment, we transfected cells with TAK1, TAB1 or control plasmid and treated them with PTX (3–10 μm) for 9–24 h." (PMID 32594651, 2020). "While other TAB partners of TAK1, namely TAB2 or TAB3, may be involved in the regulation of TAK1 activity in other chronic conditions such as cancer, our focus remains on TAK1/TAB1 complex given its established role in IL-1β-induced TAK1 activation in human RASFs." (PMID 36032089, 2022). "In conclusion, our results indicated that the MDM2/MDMX inhibitor reversed DOX resistance of human BC by activating the TAB1/TAK1/p38 MAPK pathway, suggesting that the MDM2/MDMX inhibitor in combination with chemotherapy may provide a novel therapeutic strategy for cancer treatment." (PMID 31892970, 2020).
infection (7 papers, 2017 to 2021). The state of being infected such as from the introduction of a foreign agent such as serum, vaccine, antigenic substance or organism. "Leishmania infection results in parasite GP63-induced degradation of TAB1 to reduce p38 activation, the reversal of which sharply attenuates infection." (PMID 33920735, 2021). "To gain further insight into the mechanisms of TAK1 regulation, we overexpressed TAK1 and precipitated the kinase at 0, 20, and 45 min post infection (p.i.)or 48 h post co-transfection with TAB1." (PMID 29581850, 2018). "The relative amounts of IRF3, TAB1 and NLRP12 were quantified by densitometry and presented as a ratio of COXIV after normalization with mock infection conditions." (PMID 33372854, 2021). "To validate the cleavage of IRF3, TAB1 and NLRP12 in SARS-CoV-2 infected cells, we conducted two infection experiments in two separate laboratories to study the expression levels of these proteins." (PMID 33372854, 2021). "If one considers that most of evolution is driven by lucky side-effects, the additional targets IRF3, TAB1 and NLRP12 could give a selective advantage if their cleavage would either enhance transmission or delay the response to infection." (PMID 33372854, 2021). "Infection did not change the TAB1 phosphorylation profile, but when overexpressed with TAK1, TAB1 underwent phosphorylation at Ser378 within its p38 kinase-binding region." (PMID 29581850, 2018). "Infection with H. pylori did not change the phosphorylation pattern of TAK1, but co-expression with TAB1 led to phosphorylation of additional sites, e.g., Ser454." (PMID 29581850, 2018).
bacterial infections (1 paper, 2021). "TAB1 is part of the TAB1/2/3/TAK1 complex that regulates the activity of TAK1 (TGFβ-activated kinase 1), in response to different stimuli including TGFβ, IL1, TNFα and upon viral and bacterial infections." (PMID 33372854, 2021).
TAB1 also shares sentences with these, for which no sentence is quoted: infarction (2 papers); Obesity (2); systemic sclerosis (2); aortic stenosis (1); atherosclerosis (1); autoimmune disease (1); dyslipidemia (1); esophageal squamous cell carcinoma (1); heart (1); heart failure (1); HIV-1 infection (1); kidney diseases (1); lung carcinoma (1); nasopharyngeal carcinoma (1); osteosarcoma (1); sarcoma (1); toxoplasmosis (1); type 2 diabetes mellitus (1).